CD44 (CD44 molecule (IN blood group))
Diseases named in the same sentence as CD44 in open-access papers (continued):
Sharing a sentence is not in itself a finding about the gene and the disease.
triple-negative breast carcinoma (continued). "Functionalization with HA was performed for targeting CD44, which is overexpressed in colorectal (HCT 116) and triple-negative breast cancer (MDA-MB-231) cells." (PMID 41002533, 2025). "Levels of PEAR1 protein and PEAR1 phosphorylation at Ser891 were increased in patients with triple-negative breast cancer (TNBC), were positively correlated with expression of LOXL2 and CD44, and were negatively correlated with overall survival." (PMID 39145451, 2024). "Recently, in triple-negative breast cancer cells MDA-MB-321, its activity was related to the decrease in CD44, CD24, Bcl2, release of Cytochrome c to the cytoplasm, and mitochondrial reduction." (PMID 38255214, 2024). "It is shown that SRGN, due to its interaction with CD44, creates a positive loop with TGFβ2, regulating cellular migration, invasion, EMT and metastasis of the triple-negative breast cancer cell line MDA-MB-231." (PMID 38672477, 2024). "A combination of curcumin, berberine and quercetin was shown to effectively inhibit the expression of E-cadherin, mesenchymal N-cadherin, β-catenin, CD44 marker and MMP9 in triple-negative breast cancer cells." (PMID 36015440, 2022). "For example, Circ-CD44 is highly expressed in triple-negative breast cancer (TNBC), and high expression of circ-CD44 predicts poor patient prognosis." (PMID 35116058, 2021). "Together, our data suggest that targeting NF-κB activation reduces the expression of its target genes (e.g., CD44, BCL-XL,and cMyc) and subsequently affects proliferation and invasiveness of triple negative breast cancer cells." (PMID 25184276, 2014). "In this study we investigated a new HA/CD44-mediated c-Jun signaling pathway that regulates miR-21 production and chemoresistance in MDA-MB-468 cell line (a triple negative breast cancer cell line)." (PMID 24606718, 2014). "Together, these findings suggest that the HA/CD44-induced c-Jun signaling plays a pivotal role in miR-21 production leading to survival protein (Bcl-2/IAP) upregulation and chemoresistance in triple negative breast cancer cells such as MDA-MB-468 cell line." (PMID 24606718, 2014). "We show that in triple negative breast cancer cells (e.g., MDA-MB-231 and SUM159 cells), inhibition of NF-κB via the chemical compound Bay-11-7082 results in CD44 repression." (PMID 25184276, 2014). "We also isolated CD44+CD24−, cell surface Nestinhigh, or Nestinlow CSC from 12 triple-negative breast cancer tissues." (PMID 25056574, 2014). "Notably, CD44 expression is positively correlated with PD-L1 levels in GBM patients, a relationship also observed in triple-negative breast cancer (TNBC) patients." (PMID 39977830, 2025). "We have shown that compound 1 lowers CSC, CD44+CD24+, and CD44− subpopulations and expression of CD15s in CD44+CD24+ and CD44− cells, showing that it or similar analogs could be developed into new treatments for triple-negative breast cancer." (PMID 34206154, 2021). "We used a combination of CD44, CD24 and EpCam markers to isolate CSCs since previous works have shown that these markers identify a subpopulation with increased tumor-initiating capabilities in triple-negative breast cancer cell lines." (PMID 32183150, 2020). "Previous studies suggest that CD44+/CD24- cells, subpopulation of cancer stem cells with self-renewing and tumor-initiating capacities, are partly responsible for chemoresistance and therapeutic failure of triple negative breast cancer." (PMID 29190901, 2017). "Interestingly, the aggressive claudin-low subtype of triple-negative breast cancers showed high expression of HAS2, CD44 and ZEB1." (PMID 28086235, 2017). "Treatment with CDDO-Im significantly decreased the number of CD44+/CD24−/low/EpCAM+ cells in sphere culture, suggesting that CDDO-Im could be used as a potential agent to target cancer stem cells in triple negative breast cancer." (PMID 25229616, 2014).
triple-negative breast carcinoma (continued). "Patients with triple negative breast cancer (ER–/PR–/HER2–) expressed CD44+CD49f+CD133/2+ in 9 of 9 normal adjacent tissue samples compared with 7 of 52 ER+ and/or Her2+ tumors (P < 0.001)." (PMID 24008095, 2013). "We have shown that compound 1 lowers CSC, CD44+CD24+, and CD44− subpopulations and expression of CD15s in CD44+CD24+ and CD44− cells, showing that it or similar analogues could be developed into new treatments for triple-negative breast cancer." (PMID 34206154, 2021). "Besides, BCSCs expressing both CD24- CD44+ and ALDH+ were related with worse progression-free survival (PFS) and could serve as an independent prognostic factor in some subgroups of triple negative breast cancer." (PMID 34801088, 2021). "In addition, we studied CD44 and MSI1, which have been reported to have promoter hypomethylation in triple-negative breast cancers, that is, cancers that lack estrogen receptors (ER), progesterone receptors (PR), and human epidermal growth factor-2 receptors (HER2)." (PMID 26510686, 2015). "We recently identified CD44, a nonkinase transmembrane glycoprotein, as a receptor that directly binds PTX3 and mediates PTX3-induced protumor effects in triple-negative breast cancer." (PMID 38243273, 2024). "In triple negative breast cancer, ALDH/CD44+ CSCs exhibited increased levels of PD-L1 versus non-CSC tumor cells." (PMID 33123122, 2020). "The proportion of CD44-positive [76.9 % (p < 0.05)] and EGFR-positive [67.2 % (p = 0.108)] cases in the triple-negative breast cancer (TNBC) group was higher than that of the non-TNBC group." (PMID 25429827, 2015). "The majority of cells in many triple-negative breast cancer cell lines were shown to be CD44+/CD24−/low cells, and tumorigenic potential was not tightly correlated with the percentage of the CD44+/CD24−/low subpopulation." (PMID 25229616, 2014).
head and neck cancer (86 papers, 2008 to 2025). A primary or metastatic malignant neoplasm affecting the head and neck. "In particular, increased CD44 expression in head and neck cancer was associated with increased capacity for tumor initiation and differentiation." (PMID 34680249, 2021). "For example, HA binding to CD44 induces a physical association between Nanog and Stat-3 in head and neck cancer cells leading to miRNA-21 gene expression and production." (PMID 31293964, 2019). "The presence of high levels of CD44 variant (CD44v) isoforms is emerging as an important metastatic tumor marker in many cancers including head and neck cancer." (PMID 28837080, 2017). "TrkA/CD44 association was also tested in cell lines from breast, prostate, colon, head and neck cancers although total expression levels of CD44 and TrkA varied between the cell lines." (PMID 25840418, 2015). "Therefore, we present here a systemic review and meta-analysis of published studies on the association of CD44 expression with clinicopathological features in patients with head and neck cancer." (PMID 24410905, 2014). "Cancer stem‐like cells have been reported in head and neck cancers since 2007, and CD44 is one of the most well‐known cancer stem‐like cell isolation markers in head and neck cancers." (PMID 40399621, 2025). "In HSC-3 head and neck cancer cells, 500 kDa HA binds to CD44, triggering downstream RhoC and Rho-kinase activation, which promotes cell growth, migration, invasion, and cisplatin resistance." (PMID 40507943, 2025). "In head and neck cancer, CD44 was shown to inhibit the phosphorylation of GSK3β, which is required to maintain stem cell self-renewal." (PMID 38329386, 2024). "In head and neck cancer, CD44 was shown to contribute to chemoresistance and to upregulate expression of the MDR pump via miR-21, by activating the stem cell marker Nanog." (PMID 37958796, 2023). "HNSCC is the most common type of head and neck cancer, and it has been revealed as the second-highest CD44-expressing cancer type in the Pan-Cancer Atlas." (PMID 37189717, 2023). "To date, several putative cancer stem cell (CSC) markers have been identified in head and neck cancer, including CD44, CD133, CD10, and CD98." (PMID 37894373, 2023). "There are many discrepancies in the interpretation of CD44 expression in head and neck carcinomas, exhibiting different biological characteristics depending on their subsites." (PMID 37173926, 2023). "Head and neck carcinoma CD44+ CSCs containing elevated levels of various cytokines, including TGFβ, has been reported to inhibit production of IFNγ, a key marker of Th1 response." (PMID 38038865, 2023). "In an attempt to assess the impact of butylidenephthalide on the features of ALDH1+/CD44+ cells, we examined their migration, invasion, and colony forming capacities since ALDH1+ or CD44+ head and neck cancer cells exhibited higher cancer stemness properties." (PMID 35682836, 2022). "As for CD44, it was revealed to maintain the self-renewal capacity of CSCs through the inhibition of phosphorylated glycogen synthase kinase 3β (pGSK3β) in head and neck cancers." (PMID 35682836, 2022). "CD44 has also been identified as a marker of cancer stem cells (CSCs) in several solid tumors, as well as head and neck cancers, including oral squamous cell carcinomas and epithelial dysplasia." (PMID 34830890, 2021). "Subsequently, OCT-4-induced synergistic action of ID1 and NF-κB triggers the expression of important head and neck cancer stem cell markers, BMI-1 and CD44." (PMID 33442406, 2021). "The expression of CD44, a well-known stem cell marker for head and neck cancer, was higher in tumor CRCs than in its matched normal CRCs." (PMID 34778255, 2021). "These CD44+ CSC populations have been substantially isolated from the head and neck cancers via flow cytometry sorting through CD44 antibody." (PMID 32280305, 2020).
head and neck cancer (continued). "Franzmannet al. reported CD44 as a probable biomarker of head and neck cancer whereas, Nagleret al. described Cyfra-21-1 and cancer antigen-25 to be potential biomarkers for oral cancer." (PMID 32399208, 2020). "In head and neck carcinomas the subset of CD44+ CSCs expressing high level of PD-L1 can selectively evade host immune responses." (PMID 33123122, 2020). "We have found that HA induces C/EBPα phosphorylation in CD44v3high head and neck cancer cells (HSC-3 cells) in a CD44-dependent manner." (PMID 31293964, 2019). "A previous study showed that HA binding to CD44 promotes the expression of miR-302 in a Nanog/Oct4/Sox2-dependent manner in head and neck cancer stem cells (CSCs)." (PMID 31293964, 2019). "On the other hand, overexpression of miR-145 in ALDH1+/CD44+ head and neck cancer cells reduced the stemness features." (PMID 31530793, 2019). "HA/CD44 activated stem cell marker (Nanog) signaling pathways are also involved in regulating miR-21 expression in both breast and head and neck cancer cell lines." (PMID 31293964, 2019). "In particular, 500 kDa HA via CD44 activated downstream RhoC and Rho associated kinase (ROK) in HSC-3 head and neck cancer cells and promoted cell growth, invasion, migration and resistance to cisplatin." (PMID 30513961, 2018). "These events are critically important for the acquisition of cancer stem cell properties including tumor cell invasion and chemotherapy resistance in HA/CD44-activated CD44v3highALDH1high head and neck cancer CSCs." (PMID 28837080, 2017). "HDACi are used as differentiation therapy in several hematologic malignances and have also been proposed for suppressing various CSC-like properties of CD44+ enriched cells in breast and head and neck cancer." (PMID 29179494, 2017). "BMI1, ALDH1 and CD44 have been proposed as putative markers for the identification and isolation of CSCs in head and neck cancer." (PMID 28865486, 2017). "The immunophenotype CD44+CD24- has been used to identify cancer stem-like cells in head and neck cancers." (PMID 25823923, 2015). "Anti-CD44 antibodies resulted in a significant inhibition of head and neck cancer cell motility in the presence of osteopontin stimulation combining with PD98059, compared to parental cells treated with isotype IgG antibody." (PMID 24810160, 2014). "Taken together, these results indicate that ERK activation for head and neck cancer cell migration and invasion is required for osteopontin/CD44-dependent signaling pathway." (PMID 24810160, 2014). "CD44 in head and neck cancer has been shown to be present in cancer stem-like cells in head and neck cancer." (PMID 24572994, 2014). "Then we further sought to measure the fraction of CD44-positive cell population which contained putative cancer stem cells in head neck cancer by fluorescent-activated cell sorting." (PMID 24345883, 2013). "CD44 interaction with POU5F1-SOX2-NANOG signaling also plays a pivotal role in CSC maintenance from head and neck cancers." (PMID 24091605, 2013). "The expression of CD44 has been correlated with tumor progression and poor diagnosis in oral/head and neck cancer." (PMID 24423398, 2013). "CD44 is a well-documented cell surface marker for head and neck cancer and BMI-1 is necessary for self-renewal." (PMID 23176396, 2012). "From the assessment of multiple transcriptomics data sets in public databases, we have shown that head and neck cancers specifically overexpress CD44 compared to other solid cancer types, suggesting an important role for CD44 in these cancers." (PMID 22242150, 2012). "Relative plotting displayed elevated expression levels of CD44 in head and neck cancer as well as in acute myeloid leukemia (AML) and lung carcinoid tumors relative to 65 other cancer types (see box in the “Cancer” compartment)." (PMID 22242150, 2012). "We then assessed how CD44 expression differed between head and neck cancer stem and progenitor cells with and without mutations." (PMID 37894373, 2023).
head and neck cancer (continued). "In fact, CD44 alone served as a CSC marker in head and neck carcinoma." (PMID 37108495, 2023). "miR-520b can also reduce CD44 expression during head-neck cancer development." (PMID 33758783, 2021). "In contrast to these results, the same group also demonstrated that in the head and neck cancer cell line UMSCC-11A CD44+/CXCR4+ cells showed increased podia formation with the additional of CXCL12 suggesting a role of this axis in the regulation of CD44+ CSC." (PMID 35047489, 2021). "miR-520b is able to reduce CD44 expression during head-neck cancer development." (PMID 33758783, 2021). "Therefore, researchers usually employed combining ALDH1 and CD44 as one of the markers to separate cancer stem cells in the head and neck cancer cells." (PMID 32280305, 2020). "Therefore, we believe that the regulation of lncRNA UCA1 expression in head and neck cancer cells is HA-dependent and CD44-specific." (PMID 31293964, 2019). "HA appears to interact with CD44 and induces miR-10b expression in head and neck cancer cells." (PMID 31293964, 2019). "Another cell surface marker is the single-chain sialoglycoprotein CD24, which is also associated with cancer stem cell characteristics in colorectal and pancreatic cancer, while head and neck cancer cells and breast cancer cells with CD44+CD24−/low expression are highly tumorigenic." (PMID 28837080, 2017). "Flow cytometric analysis showed that a small population of SCC-1 cells (∼7-8%) was positive for CD44, a commonly used cell surface marker for head and neck cancer stem-like cells, while EGF stimulation upregulated CD44 expression and significantly enriched the fraction of CD44+/CD24low/− cells." (PMID 27926487, 2017). "Hyaluronan (HA), an important glycosaminoglycan component of the extracellular matrix (ECM), and its major cell surface receptor, CD44, have been suggested to be important cellular mediators influencing tumor progression and treatment resistance in head and neck cancer." (PMID 28837080, 2017). "ΔNp63 regulates the expression of CD44 splicing isoforms in head and neck cancer." (PMID 27494839, 2016). "In the case of head and neck cancer, such cells have been characterised by high expression levels of CD44 cell surface glycoprotein, while we have previously shown the presence of two diverse oral CSC populations in vitro, with different capacities for cell migration and proliferation." (PMID 26540568, 2015). "Furthermore, we have also shown CD44 (another stem cell surface marker) expressing cells decrease in the RhoC depleted head and neck cancer cell lines." (PMID 24533098, 2014). "We next asked whether CD44, a binding receptor of osteopontin could be contributed to the regulation of Aurora-A expression in head and neck cancer cells." (PMID 24810160, 2014). "We next questioned whether CD44 could be attributed to modulate the ERK1/2 activity induced by osteopontin in head and neck cancer cells." (PMID 24810160, 2014). "A similar result was reported for head and neck cancer treated with chemoradiation, in which positive CD44 and negative ALDH1 expression was linked with significantly poor prognosis." (PMID 25240521, 2014). "To understand whether this increased expression is related to all cancers or just oral and head and neck cancers specifically, we mined the two currently existing major public transcriptomics databases for CD44 expression." (PMID 22242150, 2012). "Hyaluronan was found to promote CD44 dependent cisplatin resistance in head and neck cancer." (PMID 21637840, 2011). "The role of CD44 to identify CSC in head and neck cancer remains controversial." (PMID 24281171, 2010). "Once more, the CD44 protein, discussed in detail in the previous section, provides a remarkable example since radiolabeled antibodies directed against the CD44-v6 isoform appear to offer a promising therapeutic tool and are currently in clinical trials for treatment of head and neck cancer." (PMID 19516963, 2008).